RN7SL242P (RNA, 7SL, cytoplasmic 242, pseudogene)
Gene: Miscellaneous RNA gene on chromosome 1 (70,180,144 to 70,180,440, reverse strand). Ensembl gene ENSG00000244389.
Homologues: Orthologues: chimpanzee Metazoa_SRP (98% identical), macaque Metazoa_SRP (93% identical), rabbit Metazoa_SRP (67% identical). Paralogues in human: RN7SL1 (86% identical), RN7SL2 (86% identical), RN7SL3 (85% identical), RN7SL126P (82% identical), RN7SL45P (82% identical), RN7SL230P (81% identical), RN7SL448P (81% identical), RN7SL11P (80% identical), RN7SL147P (80% identical), RN7SL49P (80% identical), RN7SL791P (80% identical), RN7SL7P (80% identical), and 705 more.